DCN (decorin)
Diseases named in the same sentence as DCN in open-access papers (continued):
Sharing a sentence is not in itself a finding about the gene and the disease.
cancer (continued). "Therefore, the expression levels of DCN in cancer tissue have been proposed as a potential diagnostic or prognostic biomarker." (PMID 34884232, 2021). "In addition to TGF-β and the RTKs, DCN also interacts with a wide set of different signaling molecules implicated in cancer progression." (PMID 26697491, 2015). "According to the current status of knowledge, several proteins of the ECM as decorin or matrikines may be used both as diagnostic markers and as targets in cancer therapy." (PMID 26635612, 2015). "Decorin expression is strictly limited in mesenchymal/stromal cells, but not in epithelial cells in prostate, and its expression is significantly decreased in carcinoma-associated stroma." (PMID 24073251, 2013). "Similarly to decorin, lumican can also regulate cancer associated angiogenesis." (PMID 26056582, 2014). "This is, to our knowledge, also the first study to in more detail map the compartment‐specific and cellular distribution of DCN in any type of cancer." (PMID 41392017, 2026). "The results show that the treatment reduced angiogenesis in the tumors by 60% (p = 0.005) four days after treatment, suggesting that decorin-expressing HSV vectors are a promising strategy for novel cancer therapies." (PMID 42015278, 2026). "In cancer research, decorin is shown to have a key oncosuppressive function, offering a promising future as a potential adjuvant drug." (PMID 41463344, 2025). "Component 2 (cytokine-linked hematopoietic signaling in cancer pathways) comprised proteins involved in chemotaxis, extracellular matrix regulation, and tissue remodeling, including Eotaxin, RANTES, Decorin, FLT3 ligand, Galectin-1, and Gas1." (PMID 41282065, 2025). "Abnormal expression of DCN is also observed in the cancer progression of other sites such as the mammary duct." (PMID 40109852, 2025). "We identified 6415 fibroblasts (DCN+ and/or VIM+ cells), clustering into four normal-associated fibroblast (NOFs) and five cancer-associated fibroblast groups (CAFs) based on their variable expressed genes." (PMID 40640495, 2025). "Decorin is of particular therapeutic interest because of its synergistic action against myostatin-mediated muscle breakdown and inflammation in cancer cachexia." (PMID 40869331, 2025). "In a mouse model of prostate cancer bone metastasis, systemic administration of an oncolytic adenovirus carrying the decorin gene (Ad.dcn) significantly inhibited cancer cachexia." (PMID 40869331, 2025). "On the other hand, DCN upregulation through ectopic expression of the gene reduced the malignant activity of various cancer cell lines to a more benign state." (PMID 38667295, 2024). "This suggests that DCN downregulation in breast stromal fibroblasts can promote carcinogenesis and the resistance of cancer cells to therapy." (PMID 38667295, 2024). "Members of the SLRP family (mainly biglycan, lumican, and decorin) modulate cancer cell functions such as proliferation, migration, adhesion, and invasion in several cancer types." (PMID 39334952, 2024). "This downregulation of DCN in CAFs suggested the possible role of cancer cells in downregulating DCN in the adjacent fibroblasts." (PMID 38667295, 2024). "Our analyzis identified shared markers among the fibroblasts from both carcinoma types, notably DCN, VIM, ACTA2, CXCL12/14, and COL1A1, which were prominent markers, characteristic of these cells." (PMID 39796089, 2024). "Decorin is necessary for collagen fibril formation/realignment and in maintaining tissue stiffness, although its role in cancer development is less clear." (PMID 36693448, 2023).
cancer (continued). "We found that all the fibroblast clusters showed a high expression of the well-defined panCAF markers including COL1A1, DCN, VIM, FAP, and PDPN4, indicating the identified fibroblasts are likely cancer-associated fibroblasts (CAFs)." (PMID 37612267, 2023). "Post-transcriptional regulation of DCN is still questionable, although it is well accepted that its aberrant expression is important in developing lymph node and liver metastases in cancer, including CRC." (PMID 35052821, 2022). "Some SLRP family members are known substrates of MMPs, and Type-I SLRPs, such as Decorin and Biglycan have been reported to affect cancer progression." (PMID 36230849, 2022). "Overall, our study revealed that PGM5-AS1 acts as an anti-cancer lncRNA in CC by sponging the miR-4284/DCN axis." (PMID 35420507, 2022). "In contrast, there are numerous proven lncRNAs that are validated to sponge miR-200c in different cancers, the predicted regulatory miRNA of DCN." (PMID 35052821, 2022). "Significantly enriched KEGG pathways, such as proteoglycans in cancer (DCN, LUM, WNT2B, HSPG2; p = 3.60e 04), were also mainly associated with downregulated proteins." (PMID 35340765, 2022). "Down-regulation of β-catenin by the proteoglycan decorin, blocks cell scatter, evasion and migration in cancer." (PMID 33813600, 2022). "In inflammatory breast cancer (IBC), DCN is significantly downregulated, while its overexpression suppresses cancer cell migration, invasion, and cancer cell stemness in vitro as well as cancer cell growth and metastasis in vivo." (PMID 36358747, 2022). "DCN is a small leucine-rich proteoglycan acting as a powerful cancer repressor by blocking receptor tyrosine kinases, whose expression was decreased in HCC compared with normal liver tissues and followed the staging." (PMID 33878734, 2021). "By inactivating c-met, the downstream beta-catenin signaling pathway is inhibited, thereby DCN inhibits the spread of cancer." (PMID 34888227, 2021). "For stroma, the marker genes used were VWF, ENG, and CDH5 (for endothelial cells), DCN, ACTA2, and FAP (for cancer-associated fibroblasts), and PTPRC, CD4, and CD163 (for leukocytes)." (PMID 33810510, 2021). "In this study, we explore the expression of CRNN, COL1A2 and DCN in a well-characterised bank of non-cancer disease and pN− and pN+ TSCC tissues with extensive records on use of addictive agents." (PMID 33889206, 2021). "On the contrary, both reference marker proteins COL1A2 and DCN showed a Low cytoplasmic expression in 38 (79.2%) and 44 (91.7%) non-cancer patients." (PMID 33889206, 2021). "Although the proteome profile assay showed favorable results by modulating Decorin and M-CSF proteins, our analysis also demonstrates an up-regulation of the cancer-related proteins AXL, CEACAM-5, and SNAIL due to the effect of the drugs." (PMID 34641286, 2021). "In breast cancer cells, DCN restricts cancer cell proliferation and induces cell differentiation by down-regulating the receptor tyrosine kinase human epidermal growth factor receptor 2 (HER-2)." (PMID 34888227, 2021). "Recent reports have revealed that decorin can act as an anti-metastatic effector, suppressing migration and invasion of cancer cells." (PMID 34386415, 2021). "Reduced expression of DCN has been considered as an indicator of poor prognosis in patients with cancer." (PMID 34321013, 2021). "When DCN expression specifically in cancer cells was assessed, high DCN correlated significantly with reduced survival, which is compatible with our observed high expression in BCSCs." (PMID 34253873, 2021). "Several studies have shown that stromal DCN expression is primarily reduced or even suppressed by cancer cells in various epithelial cancers such as lung, colon, esophageal and oral cancer, and myeloma." (PMID 34884232, 2021). "This was consistent with the finding that DCN secreted by fibroblasts is a matrix-mediating agent in cancer development." (PMID 34504839, 2021).
cancer (continued). "In the following sections, we will summarize and discuss the major signaling functions of biglycan and decorin in normal physiology and in the context of cancer." (PMID 34917515, 2021). "The protective role of decorin in experimental situations raises the possibility that this proteoglycan can be utilize in the battle against human cancer." (PMID 32477937, 2020). "Some myokines, such as decorin, IL-6, irisin, oncostatin-M, have been found to play a role in cancer modulation." (PMID 31936342, 2020). "The role of SLRP family of proteoglycans, which includes decorin, biglycan and lumican, in cancer is different between its members." (PMID 33330449, 2020). "Biglycan, lumican, and fibromodulin are overexpressed in various types of cancer, whilst decorin is overexpressed in some types of cancer and suppressed in others." (PMID 33202923, 2020). "DCN is a multi-RTK inhibitor and likely has the broadest functional impact of these proteoglycans on cancer-associated pathways and response to growth factors." (PMID 32553107, 2020). "On the other hand, delivery or induced expression of decorin in different carcinomas has been demonstrated to suppress malignant behavior." (PMID 32824864, 2020). "Our interaction map further revealed an additional role of DCN as an interactor of the carcinoma‐specific receptor EGFR." (PMID 33332768, 2020). "Some previous studies showed that DCN played an important function in cancer development and metastasis." (PMID 31703725, 2019). "The analysis demonstrated that expression of four of six proteins (CCL13, IL‐6, CXCL17, and DCN) also differed between the benign lesions and cancer." (PMID 30451357, 2019). "To date, DCN has gained recognition for its essential roles in regulating the biological processes of inflammatory disorders, fibrotic disorders and cancer, and a numerous applications of DCN as an anticancer therapeutic have been carried out." (PMID 29435195, 2018). "This is especially pertinent to proteins such as vitronectin, decorin and fibrinogen and suggests a potential anti-cancer ability of curcumin through suppression of key processes during CCA development." (PMID 30440021, 2018). "A specific 11‐protein signature, including FGF binding protein 1, decorin, and furin, distinguished all cancer patient samples from all benign lesions in our main cohort and in smaller replication cohort." (PMID 30019538, 2018). "Decorin has been shown to play a protective role in cancer and fibrosis due to its ability to modulate various signal transduction pathways and sequester TGF-beta via direct binding." (PMID 28793886, 2017). "Decorin appears to have a protective role in cancer and has also been shown to have anti-fibrotic properties." (PMID 28793886, 2017). "In-depth investigations into the signaling pathways and elucidation of the primary components decorin utilizes will ultimately provide innovative and effective autophagy-based therapeutic targets and solutions for human disease and cancer progression." (PMID 28798237, 2017). "In agreement with the microscopic visualization, the MTT assay revealed that dE1/DCN significantly attenuated cell viability compared to dE1, which induced no cytopathic effect (P < 0.001), indicating that expression of DCN induced cancer cell death." (PMID 29100340, 2017). "The expression of many genes that induce adhesion, such as CXCR4 and DCN, and cellular movement in cancer, such as DKK1 and ITGB4, evidently increased when FLRT2 was downregulated, and decreased when FLRT2 was upregulated." (PMID 28325946, 2017).
cancer (continued). "Together, these results demonstrate that Ad-mediated DCN expression can induce cancer cell death and enhance the therapeutic efficacy of oncolytic Ads." (PMID 29100340, 2017). "To assess the effect of oncolytic Ads on expression of immunosuppressive TGF-β, we first evaluated the effect of green fluorescent protein (GFP) and DCN-expressing replication-incompetent Ad (dE1/GFP/DCN) on TGF-β expression in cancer cells." (PMID 28002796, 2017). "IL-12 secretion was dose-dependently elevated in cancer cells infected with either RdB/IL12 or RdB/IL12/DCN (P < 0.001)." (PMID 28002796, 2017). "Particularly the activation of EGFR / ErbB1 and ErbB2 has been shown to be important in the progression of different human cancers, and decorin has been shown to interact with both of them." (PMID 28653173, 2017). "Taken together, these results indicate that DCN plays a role in the induction of apoptosis, leading to accelerated cancer cell death." (PMID 29100340, 2017). "DCN affects the biology of various types of cancer by targeting a number of crucial signaling molecules involved in cell growth, survival, metastasis, and angiogenesis." (PMID 26697491, 2015). "DCN affects the biology of various types of cancer by directly or indirectly targeting large numbers of crucial signaling molecules involved in cell growth, survival, metastasis, autophagy, and angiogenesis." (PMID 26697491, 2015). "We will review the role of DCN in cancer development and highlight its vast therapeutic anticancer potential in this review article." (PMID 26697491, 2015). "The DCN-provoked inhibition on the PDGF-dependent phosphorylation of the PDGF receptor results in the attenuation of cancer cell migration." (PMID 26697491, 2015). "Decorin has been labeled as a “guardian from the matrix” because of its ability to sequester a number of cancer-relevant growth factors." (PMID 26327350, 2015). "The ECM protein periostin, which is abundantly expressed by a large number of different human cancers, binds and neutralizes DCN." (PMID 26697491, 2015). "BT474 was the only cancer cell line of which the metabolism significantly diminished when 5 μg/ml decorin or more was added to the type I collagen coating (p<0.001)." (PMID 25593993, 2014). "Our mechanistic studies demonstrated that siRNA knockdown of periostin abolishes the interaction with decorin, thereby increasing the level of decorin secreted from cancer cells." (PMID 25400079, 2014). "For example, expression of human decorin cDNA via adenovirus mediated transfection has been demonstrated to induce specific and even distant apoptosis of cancer cells demonstrating a direct antitumourigenic effect of decorin." (PMID 26056582, 2014). "In this study, we aimed to investigate paracrine regulation of expression of decorin and related extracellular matrix (ECM) proteins in cancer-associated fibroblasts (CAFs)." (PMID 25593993, 2014). "In particular, we found that knockdown of periostin results in translocation of decorin from the cytoplasm to the extracellular space, leading to the inhibition of cancer cell migration and invasion." (PMID 25400079, 2014). "We surmise that decorin is part of a stromal barrier, preventing cancer cell spreading and thus invasion." (PMID 25593993, 2014). "Of note, decorin is currently considered as an anti-cancer agent by suppressing a series of signaling pathways." (PMID 25526025, 2014). "Because secreted decorin inhibits cell motility and invasion, the results of our study suggest the importance of periostin as a potential therapeutic target in cancer cells that express both decorin and periostin." (PMID 25400079, 2014). "It was also shown that fibroblasts express lower levels of decorin when cultured in presence of cancer cells." (PMID 24634138, 2014).
cancer (continued). "In this report, we describe a novel function of periostin: tethering of free decorin in the cytoplasm of cancer cells, thereby preventing release of decorin to the extracellular space." (PMID 25400079, 2014). "In subsequent studies the expression of decorin has been found to be decreased in several cancers such as colon, prostate, and ovarian cancers." (PMID 24146840, 2013). "The results showed that adenoviral-mediated decorin transduction decreased the proliferation index of the cancer cells with statistical significance." (PMID 24146840, 2013). "High expression of DCN in stroma, carcinoma and HSP90B1 staining in carcinoma was seen in 76%, 34% and 84% of cases, respectively." (PMID 22363530, 2012). "Several studies have demonstrated abnormal expression of the matrix-secreted proteoglycans versican and decorin in various cancer types such as prostate, breast, gastric, colorectal, ovarian, pancreatic, laryngeal and testicular tumors." (PMID 21791066, 2011). "Decorin is a multifunctional proteoglycan of the extracellular matrix that affects the biology of various types of cancer." (PMID 21958730, 2011). "Matrix proteoglycans versican and decorin are frequently over-expressed in various malignancies and are differently involved in the progression of cancer." (PMID 21791066, 2011). "In the central areas of malignant tumors, the staining was generally strong for both decorin and versican." (PMID 21791066, 2011). "The expression of decorin and versican differed greatly in carcinomas with increased MD and carcinomas with MAMCs." (PMID 21791066, 2011). "Decorin has been reported to have a number of functions including suppressing cancer cell growth and metastasis andacting with extracellular matrix molecules to influence cell adhesion and fibril stability." (PMID 20540791, 2010). "The Decorin gene codes for one of the major extracellular matrix protein which has become the focus of various cancer studies." (PMID 18793406, 2008). "The exact biological role of decorin in cancer has yet to be clarified; however, several experimental data suggest its involvement in cancer progression and metastatization." (PMID 18793406, 2008). "DCN has also been shown to be released by ferroptotic cancer cells in PDAC development and, when released, acts as a damage‐associated molecular pattern (DAMP) recognised by macrophages via advanced glycosylation end‐product specific receptor (AGER), triggering an inflammatory response." (PMID 41392017, 2026). "Decorin is the most investigated extracellular SLRP in cancer and BC by far." (PMID 41463344, 2025). "Since decorin can inhibit the proliferation and migration of cancer cells, induce apoptosis in them, and block the formation of new blood vessels, there are also studies evaluating the effectiveness of therapy using recombinant decorin." (PMID 41463127, 2025). "Cancer-associated fibroblasts (78 cells; cluster 13) specifically expressed COL1A2, DCN, and LUM." (PMID 40102789, 2025). "This comparison highlights the distinct glycosylation patterns between receptor EGFR and its ligand DCN, which may have implications for their functional interactions and roles in cancer biology." (PMID 40285620, 2025). "The effects of decorin on cancer are conflicting and require further investigation." (PMID 39334952, 2024). "Thereby, DCN could be of great therapeutic value for BC patients through targeting active CAFs, cancer cells and angiogenesis." (PMID 38667295, 2024). "For example, the stromal subset consisted of endothelial cells identified by expressions of VWF, PECAM1 and KDR, pericytes with high RGS5, ACTA2, and COL4A1 expressions, and cancer-associated fibroblasts (CAFs) identified by significant expressions of COL1A1, DCN and LUM." (PMID 38925650, 2024). "The positioning of “mesenchymal-like” cancer cells at a certain distance from the cells expressing decorin may allow them to escape its antiproliferative effects." (PMID 38805346, 2024).